LEP (leptin)
Diseases named in the same sentence as LEP in open-access papers (continued):
Sharing a sentence is not in itself a finding about the gene and the disease.
Obesity (continued). "The majority of individuals with obesity are leptin resistant, a phenotype that has been traced to both hyperleptinemia and fragmentation of the mitochondrial network in hypothalamic neurons." (PMID 34231322, 2021). "Earlier reports have demonstrated that elevated leptin concentrations in obese participants were directly proportional to obesity and positively correlated with body fat mass." (PMID 34368053, 2021). "The levels of adipocyte-derived hormones, leptin, resistin and adiponectin, depend on the fat mass and are involved in the endocrine, immunological and metabolic complications of obesity." (PMID 33658532, 2021). "All of this evidence suggests that in the early stage of obesity, increased leptin levels and/or decreased adiponectin levels enhance NK cell activation and contribute to developing or exacerbating the inflammatory response in adipose tissue." (PMID 33717101, 2021). "Only a few studies reported the effects of high leptin levels and leptin resistance secondary to obesity on the immune response to viral infections and have shown an increase in the mortality rate." (PMID 33907162, 2021). "CRF-vo2max and PA were negatively genetically correlated with obesity, body fat, body mass index and waist-to-hip circumference, triglycerides, the satiety hormone leptin, fasting insulin, insulin resistance, and T2D (significant only for PA), and CAD." (PMID 34753499, 2021). "Blood HDL cholesterol concentration was lower (p < 0.05), whereas blood uric acid, CRP, LDL cholesterol, triglycerides, triglyceride-to-HDL cholesterol ratio, glucose, insulin, and leptin concentrations were all higher (p < 0.05) in adolescents with obesity." (PMID 34682324, 2021). "Chronic intermittent hypoxia (CIH), a pathophysiological manifestation of obstructive sleep apnea (OSA), is strongly correlated with obesity, as patients with the disease experience weight gain while exhibiting elevated plasma levels of leptin." (PMID 35153807, 2021). "Since leptin acts as a messenger for peripheral energy stores, increasing its circulating levels was thought to be a potential treatment for obesity." (PMID 33557185, 2021). "The same author suggested that increased leptin sensitivity resulting from partial leptin reduction is a new promising therapeutic tool for treating obesity." (PMID 34084149, 2021). "When circulating leptin levels are chronically elevated, as is the case in obesity, overactivation of leptin’s negative regulators can lead to leptin resistance." (PMID 34502119, 2021). "In adults, blood leptin levels correlate with BMI, and hyperleptinemia and leptin resistance are prevalent in individuals with obesity or overweight; this is also the case for pregnant women." (PMID 35185642, 2021). "The mean values for CRP, sICAM, and leptin were significantly higher in the children with obesity and adiponectin levels were significantly lower." (PMID 33665176, 2021). "Sympathetic nerves are also activated by leptin released from adipocytes, and a person who has a higher body mass index or fat mass also has a higher level of plasma leptin owing to obesity-induced leptin resistance." (PMID 33466647, 2021). "In the present study, we aimed to test if maternal obesity and adiposity, characterized by BMI and circulating levels of leptin, alter serum fatty acid concentrations already during the first trimester of pregnancy in non-smoking women." (PMID 34638763, 2021). "As a relationship between metabolic syndrome, obesity, and diabetes with periodontal disease is well documented in literature, the role of LEP has been repeatedly investigated in this context." (PMID 34545294, 2021). "High leptin levels and insulin resistance are some of the initial pathways of metabolic syndrome in obesity and NAFLD." (PMID 34722019, 2021). "It should also be noted that leptin, whose signaling is modified in ob/ob and db/db strains and elevated in obesity, has been researched as a possible regulator of the hematopoietic system." (PMID 33554957, 2021).
Obesity (continued). "Leptin and adiponectin—important hormones in obesity management—were also suppressed in B. uniformis CBA7346 treated mice on an HFD." (PMID 34578867, 2021). "The increase of serum leptin concentration in the obesity population can promote the rise of thyroid-stimulating hormone levels, which leads to the occurrence and development of thyroid nodules." (PMID 34452638, 2021). "Preclinical studies have shown NSAIDs to be effective at reducing or reversing obesity-induced adipose inflammation as well as decreasing adipose tissue leptin levels." (PMID 33859943, 2021). "One of the most important pro-inflammatory obesity-related adipokines is leptin, which has pleiotropic functions." (PMID 34827640, 2021). "Obesity-associated changes in white adipose tissue (WAT) impact the production and release of adiponectin and leptin, two adipokines mainly produced and secreted by white adipocytes." (PMID 33572989, 2021). "The study found that elevated serum leptin levels contribute to the development of metabolic complications of obesity, especially diabetes and insulin resistance." (PMID 33833859, 2021). "Stratifying the analyzes according to the presence of obesity and patients’ gender, significant differences were found for leptin in both sexes." (PMID 34829886, 2021). "Obesity-related dysfunction can contribute to cancer pathogenesis and treatment resistance through various mechanisms, including those mediated by insulin, leptin, adipokine, and aromatase signalling pathways, particularly in women." (PMID 33911195, 2021). "Our results showed that after HFD treatment, mice showed obesity features, such as increased body weight, cholesterol, leptin levels, and inflammatory markers." (PMID 33642987, 2021). "Tumor necrosis factor (TNF) alpha, a proinflammatory cytokine produced by macrophages, monocytes, T lymphocytes, and adipose tissue, has high serum concentrations in patients with obesity, and its secretion is exacerbated by leptin." (PMID 34835964, 2021). "Protein tyrosine phosphatase-1B is a well-characterized tyrosine phosphatase, which has been shown to suppress both insulin and leptin signaling pathways and is therefore useful in the treatment of type II diabetes and obesity." (PMID 34434118, 2021). "Consistent with the progression of obesity, we found normal circulating leptin level in 2 to 3 months old mice, but significantly increased leptin levels in 6-month-old αOGTKO mice." (PMID 33460647, 2021). "A possible explanation is that patients with Ob have leptin resistance, a feature that contributes to the pathology of obesity." (PMID 33603787, 2021). "Adipose tissue expansion disturbs the balance between leptin and adiponectin by decreasing adiponectin and increasing leptin, leading to obesity, insulin resistance, and hepatic steatosis." (PMID 34593018, 2021). "As a result, leptin levels are increased during obesity, with a parallel reduction in circulating adiponectin." (PMID 33669882, 2021). "Obesity is another factor that can dysregulate the endocrine role of leptin secretion from adipocytes, so that hyperleptinemia due to high fat mass fails to negatively regulate food intake, a state termed leptin resistance." (PMID 33922108, 2021). "These include insulin-, leptin- or glucocorticoid resistance, which are related to the induction of diabetes, obesity and hampered down-regulation of inflammation, respectively." (PMID 34444774, 2021). "The interaction of adiponectin with leptin, insulin and estrogen is also discussed, which provides a promising therapeutic target for the treatment of obesity related tumors." (PMID 34485124, 2021). "In recent years, a large number of studies have shown that leptin affects the occurrence and development of many obesity related tumors." (PMID 34485124, 2021). "This review examines recent data obtained from human and animal studies related to leptin, its role in obesity, and its usefulness in obesity treatment." (PMID 34084149, 2021).
Obesity (continued). "Here we review the literature to collate and provide a comprehensive summary of the relationship between leptin signaling and obesity." (PMID 34084149, 2021). "Unfortunately, this physiological function of leptin often fails, and obesity is characterized and partly ensued by leptin resistance although circulating leptin levels remain highly increased." (PMID 34835949, 2021). "The chronically augmented leptin in the CNS contributes to leptin resistance, which further promotes obesity, resulting in a vicious cycle of escalating metabolic disorder." (PMID 33849593, 2021). "Hypothalamic inflammatory signaling and ER stress have been extensively linked to reduced central leptin sensitivity and HFD-induced obesity." (PMID 33741533, 2021). "Under physiological conditions, leptin informs the brain about the energy status in the periphery, but in obesity, signaling to regulatory centers in the brain that normally inhibit food intake and regulate body weight and energy homeostasis is disrupted." (PMID 33920604, 2021). "In the context of obesity, increased leptin signaling between ASCs and breast cancer cells represents an area where the proliferative and immunomodulatory effects of ASCs contribute to an environment that permits neoplastic growth." (PMID 34912237, 2021). "At 1 month of age, male offspring born to obese dams in the exercise group had lower triglycerides, leptin levels compared to those born to obese sedentary dams indicating the beneficial effects of exercise in reducing early obesity." (PMID 34368253, 2021). "Initial evidences suggested that obesity developed from endocrine alterations in perypheral signals, essentially insulin and leptin, controlling the balance between hypothalamic orexigenic and anorexigenic responses, mainly through the melanocortin pathway." (PMID 33574566, 2021). "A 14-year-old girl from Austrian origin, with mild obesity, was identified with a homozygous transition in exon 3 (thymine to cytosine), resulting in leucine to serine exchange in codon 72 of leptin protein." (PMID 34504472, 2021). "In fact, targeted hypothalamic disruption of these pathways decreased HFD-induced obesity, hypothalamic leptin resistance, and systemic insulin resistance, implying a relevant contribution of neuroinflammation." (PMID 33557413, 2021). "Normal-weight individuals have a higher response, emphasizing the link between stress, obesity, and leptin resistance." (PMID 34684349, 2021). "In the present study, leptin showed associations with disease activity, CRP, CV history, obesity, IMT, and PWV indicating that leptin indeed forms a bridge between inflammation and atherosclerosis." (PMID 34680168, 2021). "The link between tooth brushing and obesity can be explained by a leptin-related pathway that controls the balance of appetite and energy." (PMID 34769582, 2021). "Several studies have investigated the association of the LEP and LEPR genes with obesity, feed intake, growth and fat traits, and their cardio-metabolic implications in a variety of species." (PMID 34496773, 2021). "The increase in leptin secretion and corresponding decrease in tissue sensitivity to leptin leads to obesity." (PMID 34578892, 2021). "Obesity influences a variety of physiological processes, including the dysregulation of signaling molecules, such as leptin." (PMID 33810619, 2021). "The caloric imbalance observed in obesity is thought to be promoted by the development of leptin resistance and is also considered to be one of the primary risk factors for both overweight and obese individuals." (PMID 35153807, 2021). "The relationship between obesity and stress is biological via the main stress hormones regulating appetite (leptin, ghrelin)." (PMID 33673594, 2021). "Among them, leptin and adiponectin are recognized as key players in the development of insulin resistance, obesity, and diabetes." (PMID 33536069, 2021).
Obesity (continued). "Leptin is a 16-kDa adipocytokine that is primarily produced by white adipose tissue, and it is well-known for its role in metabolic regulation and obesity." (PMID 33099751, 2021). "These include mutations in leptin and its receptor (LEPR), prohormone convertase 1 (PC1), and fat mass and obesity associated (FTO) gene." (PMID 34777390, 2021). "It is known that a high level of blood leptin in obesity leads to the development of resistance to this hormone in the brain, and therefore suppressing the feeding cannot reduce its blood concentration." (PMID 33920712, 2021). "Circulating leptin concentration increases with obesity, correlates with BMI and adipose tissue mass, and is reduced with weight loss." (PMID 33528828, 2021). "Leptin is inhibiting appetite and hunger sensation in the central nervous system which in dietary obesity it cannot pass the blood-brain barrier due to existing low-grade inflammation." (PMID 34805304, 2021). "Obesity can cause changes in the levels of insulin, IGF-1, leptin, adiponectin, steroid hormones and cytokines in the body, creating a favorable environment for the occurrence and development of tumors." (PMID 35083251, 2021). "Enhanced plasma levels of leptin are commonly observed in obesity, but obese individuals are prone to develop resistance to the physiological effects of leptin." (PMID 34201760, 2021). "Genetic mutations of signal molecules produced by the adipose cell (e.g. leptin) appear also to be involved in the individual responses to physiologic, environmental, and psychological stresses seen in both obesity and painful syndrome." (PMID 32964308, 2021). "The main components of PEO are citronellol, a volatile compound that fights obesity by reducing food intake, patchouli alcohol, α-patchoulene, and β-patchoulene, which stimulates the hypothalamus and regulate leptin levels." (PMID 34769261, 2021). "Obesity correlates with elevated insulin levels, free IGFs, and adipocyte-derived factors, including leptin, the tumor necrosis factor-alpha (TNF-α), and interleukin-6 (IL-6)." (PMID 34298805, 2021). "Leptin is an adipose-derived hormone that acts on central receptors to reduce feeding and appetite, and leptin resistance is a feature of obesity." (PMID 34684760, 2021). "Leptin resistance and excess leptin production result in abnormal appetite, hyperinsulinemia, hypothalamic inflammation, obesity, dyslipidemia, altered blood-brain barrier transport, and the emergence of other metabolic disorders." (PMID 34497507, 2021). "Obesity is characterized by an imbalance in a specific family of pro and anti-inflammatory molecules, i.e. the so-called adipokines, among which leptin and adiponectin are the most recognized." (PMID 34456928, 2021). "This suggests that peripheral cancer cell leptin signaling is required for obesity-dependent effects of MMTV-Wnt1 cells." (PMID 33987528, 2021). "We analyzed the anti-obesity effects of WGJe on the expression levels of two hormones involved in food intake regulation: ghrelin, an appetite-stimulating hormone, and leptin, an anorexigenic one." (PMID 33672773, 2021). "These approaches regenerate the hope of developing leptin's potential as an effective anti-obesity compound." (PMID 33741533, 2021). "This literature review is the result of the study and analysis of information obtained on the relationship between leptin and cancer, approaching the role of obesity, inflammation, and immunotherapies in the disease, in the last decades." (PMID 34202969, 2021). "The increase in visceral adipose tissue in obesity tilts this balance in favor of the pro-inflammatory cytokines such as IL-6, IL-8, TNFα, and leptin." (PMID 33920379, 2021). "Lack of POMC protein in mice leads to the spontaneous development of obesity with insensitivity towards leptin." (PMID 33572982, 2021).
Obesity (continued). "Administration with RSV alone can increase the concentration of leptin in the body and reduce the elevation of the leptin level and the onset of leptin resistance, which are attributed to obesity or a high-cholesterol diet." (PMID 34209270, 2021). "We will also address the currently identified mechanism(s) of diet-induced leptin resistance and how they differentially contribute to obesity and infertility." (PMID 34502119, 2021). "Levels of this “satiety hormone” directly correlate with increased NE and IL-33 concentration in obese mice and men and leptin itself is increased in obesity and inflammation." (PMID 33673387, 2021). "Recent studies have shown that ob/ob and leptin-resistant mice with diet-induced obesity (DIO) have increased upper airway collapsibility and develop inspiratory airflow limitation and OSA as well as OHS." (PMID 34201760, 2021). "In subjects with obesity, increased leptin levels correlate with circulating TNF-α, which displays a suppressive effect on lymphocytes count." (PMID 34925228, 2021). "Leptin, the major adipocyte-derived adipokine, is a known biomarker of obesity due to the high positive correlation of its circulating levels with BMI." (PMID 34156978, 2021). "Rather, LepR and intracellular signaling cascades such as phosphorylation of ERK1/2 in tanycytes of the mediobasal hypothalamus and endothelial cells at the BBB seem to be principal regulators of transport leptin across brain barriers and obesity." (PMID 34066779, 2021). "Obesity and leptin signalling have also been reported to enhance chemoresistance to anticancer drugs in human pancreatic cancer." (PMID 33536560, 2021). "A study showed that therewas decreased ghrelin sensitivity after the administration of leptin, implying thatthe increased leptinemia observed in obesity is responsible for the resistance ofghrelin." (PMID 34879109, 2021). "Chronic inflammatory states due to metabolic (i.e., obesity) as well as infectious diseases increase leptin concentrations and consequently lead to leptin resistance further fueling inflammation." (PMID 33804765, 2021). "It was demonstrated in patients suffering from obesity that leptin levels and BMI were inversely correlated with the number of regulatory T cells." (PMID 33920604, 2021). "Moreover, it has been highlighted that disruption of the circadian clock may alter leptin circadian rhythm and synthesis and may induce leptin resistance, causing the impaired regulation of metabolism and energy balance and promoting obesity and metabolic complications." (PMID 34068919, 2021). "Despite the impressive leptin sensitizing effects, using celastrol or withaferin A as an anti-obesity drug has some adverse effects." (PMID 34084149, 2021). "Chronic low-grade inflammation, present in obesity and promoted by it, causes a decrease in muscle anabolic function, mediated by changes in the production of factors, such as TNF, IL-6, leptin and GH." (PMID 33802940, 2021). "In obesity, adipocytes produce less adiponectin, that has anti-inflammatory and anti-neoplastic effects, but more leptin, that can contribute to melanoma growth and metastases." (PMID 34631264, 2021). "Other infectious models also highlight the detrimental contribution of elevated leptin to inflammatory outcomes in obesity." (PMID 33958704, 2021). "As a cytokine that promotes satiety, its function is altered in the case of obesity, a phenomenon called “leptin resistance”." (PMID 34207197, 2021). "The normal breast tissue samples characterized by an elevated leptin/adiponectin transcriptional ratio for obesity showed the altered distribution of polarity markers at the apex, while leptin level in breast tissue increased with overweight and obesity." (PMID 34350120, 2021). "Nebivolol-induced suppression of cardiac miR-208a and increase in MED13 were correlated with attenuated weight gain despite leptin resistance; consequently, resistance to obesity was observed in rodents treated with nebivolol." (PMID 34603773, 2021).